DUSP6 (dual specificity phosphatase 6)
Diseases named in the same sentence as DUSP6 in open-access papers (continued):
Sharing a sentence is not in itself a finding about the gene and the disease.
lung carcinoma (continued). "DUSP6 could act as a negative regulator of the extracellular regulated MAP kinase (ERK) signaling pathway, playing an important role in a variety of cancers, such as lung cancer and prostate cancer." (PMID 35458535, 2022). "As with mouse KRAS G12D cells, stimulation of PERK autophosphorylation at T982 (p-PERK) by TG treatment was associated with increased p-eIF2α and p-ERK as well as decreased DUSP6 expression in human lung cancer cells with KRAS G12C (H23, H358) but not in cells with WT KRAS (H1299, H1703)." (PMID 34330898, 2021). "However, the lack of studies in large databases comparing the expression of DUSP6 with survival in lung cancer has not allowed a clear picture on the role of DUSP6 in this type of tumor." (PMID 31027181, 2019).
ovarian carcinoma (23 papers, 2005 to 2025). A malignant neoplasm originating from the surface ovarian epithelium. "Previous studies focused on the potential use of DUSP1, DUSP4, and DUSP6 as diagnostic markers in ovarian cancer." (PMID 37476896, 2023). "Furthermore, intracellular ROS accumulation such as hydrogen peroxide causes DUSP6 phosphorylation on Ser159 and Ser197 residues, leading to ubiquitination and degradation of DUSP6 in ovarian cancer cells." (PMID 34685488, 2021). "However, loss of DUSP6 expression in ovarian cancer cells has been demonstrated to increase chemoresistance." (PMID 25568665, 2014). "Ovarian cancer tissues have shown elevated levels of DUSP6, and suppress it expression can enhance the responsiveness to chemotherapy drugs in Ovarian cancer." (PMID 40936711, 2025). "Inhibition of DUSP6 promotes chemosensitivity via regulation of ERK signaling in two different ovarian cancer cell lines (SKOV3 and OVCAR8 cells)." (PMID 37476896, 2023). "SGK1 and another top upregulated DEG, DUSP1, have both been implicated in chemoresistance and apoptosis inhibition in ovarian cancer, with our own research showing that a dual inhibitor of DUSP1 and DUSP6 reversed chemoresistance in ovarian cancer cells." (PMID 36131935, 2022). "Secondly, WNT9A, PRKCB, SGK1, and DUSP6 have been shown to promote or inhibit the development of ovarian cancer." (PMID 32331314, 2020). "In conclusion, our findings revealed the enhancement of chemotherapy-resistance and the predominance of G1 cell cycle phase arrest in DUSP6-overexpressing ovarian cancer cells." (PMID 32231719, 2020). "Our study also suggests that the overexpression of DUSP6 in ovarian cancer SP cells is accompanied with decreased expression level of CyclinD3." (PMID 32231719, 2020). "Taken together, these results suggest that DUSP6 should be considered as a potential target for predicting and regulating the platinum chemotherapy-resistance properties of advanced ovarian epithelial cancers." (PMID 32231719, 2020). "Methods: mRNA and protein expression of DUSP6 and G0/G1 cell cycle checkpoint regulating proteins (CyclinD1, CyclinD3 and CyclinE2) was evaluated among ovarian cancer cell lines and tissue samples." (PMID 32231719, 2020). "Their study used a short hairpin RNA to knock-down the expression of the endogenous DUSP6 gene in A2780s ovarian cancer cells, which were then treated with two concentration of cisplatin (5 and 10 uM)." (PMID 32231719, 2020). "Previously we showed that DUSP6 is overexpressed in ovarian cancer side population (SP) cells that possess cancer stem cell-like properties and are quiescent and chemotherapy-resistant." (PMID 32231719, 2020). "Among 39 ovarian cancer tissue samples, expression of DUSP6 in the chemotherapy-resistant group (12 samples) was higher than in the chemotherapy-sensitive group (27 samples) (P<0.05)." (PMID 32231719, 2020). "Since the ovarian cancer biomarker human epididymis protein 4 (HE4) interacts with the ERK pathway, we sought to determine the relationship between DUSP6 and HE4 and elucidate DUSP6’s role in epithelial ovarian cancer (EOC)." (PMID 31164954, 2019). "We also determined that inhibition of DUSP6 promotes chemosensitivity of two different ovarian cancer cell lines, which coincided with increased expression of pro-apoptotic EGR1, and reduced expression of oncogenic c-JUN." (PMID 31164954, 2019). "Collectively, these results highlight that HE4 positively regulates DUSP6 levels in ovarian cancer cells, and both proteins regulate ERK signaling in time-dependent manners." (PMID 31164954, 2019). "In this study, we found that HE4 promotes upregulation of DUSP6 in ovarian cancer cells, and that levels of these proteins positively correlate in EOC tissue." (PMID 31164954, 2019). "Intracellular reactive oxygen species (ROS) accumulation such as hydrogen peroxide causes DUSP6 phosphorylation on Ser159 and Ser197 residues, leading to ubiquitination and degradation of DUSP6 in ovarian cancer cells." (PMID 31151270, 2019).
ovarian carcinoma (continued). "In ovarian cancer cells oxidative stress resulted in DUSP6 ubiquitination and proteasomal degradation followed by ERK1/2 activation, tumor progression and development of chemoresistance in vitro and in vivo." (PMID 27902484, 2017). "Additionally, using the MTS assay we demonstrated that the overexpression of DUSP6 lead to an increase in the IC50 to cisplatin in ovarian cancer cells." (PMID 32231719, 2020). "Thus, the RT-PCR analysis confirmed that expression of DUSP6 was higher in ovarian cancer SP cells, compared with NSP cells, a result consistent with the RNA‐seq analysis." (PMID 32231719, 2020). "Ovarian cancer cells were transiently transfected to overexpress DUSP6." (PMID 32231719, 2020). "While there have been only few studies concerning DUSP6 and ERK signaling pathway in ovarian cancer, one study presented a result that is contradictory to ours, as it showed that the loss of DUSP6 enhances chemotherapy-resistance in ovarian cancer cells." (PMID 32231719, 2020). "Next, we sought to determine the function of DUSP6 in ovarian cancer cells." (PMID 31164954, 2019). "In conclusion, DUSP6 inhibition sensitizes ovarian cancer cells to chemotherapeutic agents and alters gene expression of ERK response genes, suggesting that DUSP6 could plausibly function as a novel therapeutic target to reduce chemoresistance in EOC." (PMID 31164954, 2019). "We determined that HE4 has the ability to mediate gene expression in peripheral blood mononuclear cells (PBMCs), and then evaluated HE4's effect on one of its identified targets, DUSP6, ultimately investigating how this relationship affects immune cytotoxicity against ovarian cancer cells." (PMID 30941033, 2019). "Moreover, DUSP6 is part of a high-risk gene signature for non-small cell lung cancer, and its expression is significantly correlated with high extracellular signal-regulated kinase (ERK) 1/2 activity in primary human ovarian cancer cells." (PMID 30517191, 2018). "In the study with pharmacological DUSP6 inhibition, OVCAR8 and SKOV3 ovarian cancer cells showed greater sensitivity to carboplatin and paclitaxel in combination with BCI than to the drug alone." (PMID 37760412, 2023). "Taken together, these findings show that HE4 enhances tumorigenesis of ovarian cancer by compromising cytotoxic CD8+ and CD56+ cells through upregulation of self-produced DUSP6." (PMID 30941033, 2019). "We report for the first time that HE4-mediated upregulation of DUSP6 in CD8+ T cell and CD56+ NK cell subsets of PBMC cells leads to the inhibition of their cytotoxic activity against SKOV3 ovarian cancer cells." (PMID 30941033, 2019). "To begin to elucidate the relationship between HE4 and DUSP6, we examined DUSP6 mRNA and protein levels in SKOV3 ovarian cancer cells overexpressing HE4 (SKOV3-C1) compared to their null vector (NV) controls, which express low levels of HE4 naturally." (PMID 31164954, 2019). "ROS scavenging by an antioxidant N-acetyl-L-cysteine increased DUSP6 expression as well as dephosphorylation of ERK1/2, and inhibited ovarian cancer cells proliferation." (PMID 27902484, 2017). "To confirm that DUSP6 was overexpressed in SKOV3 and OVCAR8 ovarian cancer SP cells, we conducted a qRT-PCR analysis and the result showed that both SP cell populations expressed higher levels of DUSP6 mRNA expression (2 to 10-fold increase) compared with non-SP (NSP) cells (P<0.001)." (PMID 32231719, 2020). "Although one ovarian cancer study suggested that DUSP6 acts as a tumor suppressor, the goal of the present study was to determine the potential relationship between HE4 and DUSP6 in the context of EOC." (PMID 31164954, 2019). "Moreover, targeting DUSP6, using a specific DUSP6 inhibitor, named BCI, re-sensitized ovarian cancer cells to chemotherapy treatment by enhancing ERK mediated apoptosis." (PMID 31416288, 2019).
ovarian carcinoma (continued). "In ovarian cancer, DUSP6 expression is lost, particularly at the protein level, leading to the hyperactivation of ERK1/2 and eventually resulting in tumorigenicity and chemoresistance of human ovarian cancer cells." (PMID 24260056, 2013). "The coordinated expression of 3 sprouty family members, DUSP6, and ETV4 and 5 in a subset of ovarian cancers therefore raises the possibility that the activity of a specific, MAPK-related signaling pathway may have a role in ovarian cancer." (PMID 16042759, 2005). "This suggests that overexpression of DUSP6 promotes chemotherapy-resistance through the negative regulation of the ERK signaling pathway, increasing the G0/G1 phase ratio among ovarian cancer cells, and leading to cellular quiescence." (PMID 32231719, 2020). "This suggests that overexpression of DUSP6 may promote chemotherapy-resistance through the negative regulation of the ERK signaling pathway, which increases the G0/G1 phase ratio among ovarian cancer cells leading to their cellular quiescence." (PMID 32231719, 2020).
pancreatic cancer (20 papers, 2007 to 2025). "Meanwhile, the encoding gene,DUSP6, is located on 12q21-q22, the region commonly deleted hemizygously in pancreatic cancer." (PMID 36017891, 2022). "The downregulation of DUSP6 was caused by the hypermethylation of CpG sequences in intron 1 of the DUSP6 gene in the progression of pancreatic cancer." (PMID 24260056, 2013). "In addition, we investigated the biological functions of DUSP6 by gain-of-function and loss-of-function experiments, since these results are consistent with recent studies demonstrating that DUSP6 acts as a tumor-suppressor gene in pancreatic cancer." (PMID 36017891, 2022). "By leveraging a single-cell RNA-seq Human Pancreatic Cancer Atlas, we were able to confirm that DUSP6 expression is increased in PDAC epithelial cells." (PMID 41028058, 2025). "Overexpression of DUSP6 in invasive pancreatic cancer cells (PCI-35 and PK-8) resulted in a reduction in phosphorylated ERK1/2 and resulted in cell growth suppression and apoptosis." (PMID 40943262, 2025). "Through in silico analysis of pancreatic tumor samples, we determined that DUSP6 expression was upregulated in the epithelial compartment of the tumor rather than in the stromal compartment." (PMID 41028058, 2025). "The effect of DUSP6 expression on prognosis and chemotherapy tolerance of pancreatic cancer patients also needs to be further investigated." (PMID 36017891, 2022). "This, together with anti-proliferative effects of DUSP6 overexpression in human pancreatic cancer cell lines, was taken as evidence for a tumour suppressive role for DUSP6." (PMID 35418690, 2022). "To explore the role of DUSP6 in pancreatic cancer cell apoptosis, we first detected the apoptosis-related proteins, poly ADP-ribose polymerase (PARP) and cleaved PARP by western blot analysis." (PMID 36017891, 2022). "To analyze the suitability of model cells for the follow-up experiments, we investigated two different human pancreatic cancer cell lines for their DUSP6 and ARF6 expressions." (PMID 36017891, 2022). "In the present study, we describe a positive feedback loop about ERK1/2-ARF6 pathway that can inhibit the expression of DUSP6 in pancreatic cancer cells, which is equivalent to removeing the inhibition of ERK1/2 pathway." (PMID 36017891, 2022). "In conclusion, this study reveals the role of DUSP6 in the ARF6-ERK1/2 positive feedback pathway, and verifies the effects of DUSP6 on the growth, proliferation and apoptosis of pancreatic cancer cells." (PMID 36017891, 2022). "By contrast, DUSP6 is upregulated in non-small-cell lung carcinoma but down-regulated in pancreatic cancer, producing tissue-specific suppressor or pro-oncogenic effects." (PMID 36589747, 2022). "Meanwhile, the levels of cleaved-PARP and Caspase-3 proteins in pancreatic cancer cells with overexpression of DUSP6 were significantly increased, while the BCL2 protein was decreased, suggesting that DUSP6 promotes the apoptosis of pancreatic cells." (PMID 36017891, 2022). "Here we use deletion of either Dusp5 or Dusp6 to explore the roles of these phosphatases in a murine model of KRASG12D-driven pancreatic cancer." (PMID 35418690, 2022). "Haloperidol showed to affect MIA PaCa-2 pancreatic cancer cell viability at least in part by restoring the expression of dual-specificity phosphatase 6 (DUSP6) gene, which is a phosphatase selective for extracellular signal-regulated kinase 1/2 (ERK1/2)." (PMID 34439102, 2021). "Conversely, DUSP6 expression was abrogated in invasive pancreatic carcinomas compared to precursor lesions." (PMID 29100381, 2017). "This indicates that, for their proliferation and survival, pancreatic cancer cells are largely dependent on the activation of MAPK induced as a consequence of the synergistic effect of mutations in KRAS and an abrogation of DUSP6." (PMID 25699241, 2015).
pancreatic cancer (continued). "In pancreatic cancer, the expression of DUSP6 was downregulated, which activated ERK excessively, and eventually led to improvement of the carcinoma development and progression." (PMID 24260056, 2013). "The high methylation of the region between +544 and +627 in intron 1 of DUSP6 was reported, accounting for the expressional suppression of DUSP6 in pancreatic cancer that was shown previously." (PMID 24260056, 2013). "Along this line, a study dealing with pancreatic cancer investigated the effects of the loss of the DUSP6-dependent negative feedback on ERK1/2." (PMID 40943262, 2025). "Considering the extensive proliferation of pancreatic cancer, elaborating the relationship between ARF6 and DUSP6 in pancreatic cancer may bring a new strategy for treating this recalcitrant tumor." (PMID 36017891, 2022). "Meanwhile, the physiological role of DUSP6 has seldom been discussed in pancreatic cancer." (PMID 36017891, 2022). "As a consequence, low DUSP6 expression accelerates cell growth in pancreatic cancer." (PMID 29100381, 2017). "Interestingly, activation of ERKs in pancreatic cancer and cell reprogramming takes place at different levels of the pathway: upstream by RAS or BRAF mutations and at the level of MAP-kinases by Dusp6 downregulation, respectively." (PMID 27030341, 2016). "Analysis of DUSP6/MKP-3 expression in pancreatic tumours revealed that protein levels were increased in early pancreatic intraepithelial neoplasia (PanIN), but then reduced in more advanced invasive or poorly differentiated tumours, a result confirmed in a more extensive study." (PMID 26791049, 2016). "In studies of genetic and epigenetic alterations of DUSP6 in pancreatic cancer, mutations of this gene have not been observed, however, marked reduction of its expression has been found." (PMID 25699241, 2015). "DUSP6 resides on the chromosome locus 12q21–22, which is commonly deleted in pancreatic cancer." (PMID 25699241, 2015). "While the expression of DUSP6 is markedly reduced in pancreatic cancer cells, the expression of DUSP6 can be restored by treatment with 5-azacytidine, an inhibitor of DNA methyltransferase, which indicates that the reduced expression stems from hypermethylation." (PMID 25699241, 2015). "This reduced expression is associated with constitutive activation of MAPK1/ERK2 and, despite the presence of mutated KRAS, exogenous overexpression of DUSP6 induces dephosphorylation of MAPK1/ERK2, subsequent suppression of proliferation, and eventual apoptosis of pancreatic cancer cells." (PMID 25699241, 2015). "Moreover, analyses by flow cytometry and immunocytochemistry revealed that the exogenous expression of Dusp6 induced apoptosis in cultured pancreatic cancer cells." (PMID 24266894, 2014). "Notably, in pancreatic cancer, DUSP6 levels are downregulated by gene deletion or promoter hypermethylation, consistent with such a function." (PMID 22784513, 2012). "Pancreatic cancer is characterized by constitutive activation of mitogen-activated protein kinase (MAPK), due to gain-of-function mutations in KRAS or BRAF and loss-of-function of dual specificity phosphatase 6 (DUSP6)." (PMID 23227827, 2012). "Furthermore, DUSP6 has been reported to be a target for methylation-dependent silencing in pancreatic cancer." (PMID 20551953, 2010). "DUSP6 encodes for a cytoplasmic dual-specificity protein phosphatase that inactivates ERK1/2 and has been shown to induce apoptosis in endothelial cells and pancreatic cancer cells." (PMID 17953764, 2007). "Our results in murine pancreas agree with previous studies in which expression of DUSP6 was detected in these early lesions in human patients, and confirm that expression of this phosphatase is indeed associated with the early stages of KRASG12D-induced pancreatic cancer development." (PMID 35418690, 2022). "Our results suggest that ARF6 may promote the growth of pancreatic cancer cells through DUSP6." (PMID 36017891, 2022).
pancreatic cancer (continued). "DUSP6 can not only act as a tumor suppressor in pancreatic cancer, but also as a vital intermediate molecule in our positive feedback loop composed of ERK1/2, ARF6 and DUSP6." (PMID 36017891, 2022). "DUSP6 can act not only as a tumor suppressor in pancreatic cancer, but also as a vital intermediate molecule in our positive feedback loop composed of ERK1/2, ARF6 and DUSP6." (PMID 36017891, 2022). "Specifically, to elucidate the negative correlations between ARF6 and DUSP6 in pancreatic cancer, we examine their expressions in pancreatic cancer tissues by immunohistochemical staining." (PMID 36017891, 2022). "Moreover, haloperidol derepresses dual-specificity phosphatase 6 (DUSP6) by intronic demethylation and inhibits the proliferation of human pancreatic cancer cells." (PMID 35804859, 2022). "Our data demonstrate that both DUSP5 and DUSP6 perform at least partially non-redundant functions in restraining the early stages of murine pancreatic cancer development driven by oncogenic mutant KRASG12D." (PMID 35418690, 2022). "In addition, the genes DUSP6, PIK3CA and YAP1 play critical roles in pancreatic cancer oncogenesis and tumor maintenance, which consequently impacts survival outcome." (PMID 30517129, 2018). "In pancreatic cancer, the DUSP6 gene was not identified to be expressed in the vast majority of pancreatic cancer cell lines and invasive primary pancreatic cancer tissues." (PMID 24260056, 2013). "A clear negative relation was found between ARF6 and DUSP6 in pancreatic cancer patients." (PMID 36017891, 2022).